DLG4 (discs large MAGUK scaffold protein 4)
Description:
Postsynaptic scaffolding protein that plays a critical role in synaptogenesis and synaptic plasticity by providing a platform for the postsynaptic clustering of crucial synaptic proteins. Interacts with the cytoplasmic tail of NMDA receptor subunits and shaker-type potassium channels. Required for synaptic plasticity associated with NMDA receptor signaling. Overexpression or depletion of DLG4 changes the ratio of excitatory to inhibitory synapses in hippocampal neurons. May reduce the amplitude of ASIC3 acid-evoked currents by retaining the channel intracellularly. May regulate the intracellular trafficking of ADR1B. Also regulates AMPA-type glutamate receptor (AMPAR) immobilization at postsynaptic density keeping the channels in an activated state in the presence of glutamate and preventing synaptic depression (By similarity). Under basal conditions, cooperates with FYN to stabilize palmitoyltransferase ZDHHC5 at the synaptic membrane through FYN-mediated phosphorylation of ZDHHC5 and its subsequent inhibition of association with endocytic proteins.
Synonyms: PSD-95; SAP-90; SAP90; PSD95; MRD62
Tractability: Small molecule: a high-quality ligand is known. Antibody: UniProt places it where antibodies can reach, with high confidence; its Gene Ontology location is reachable by antibodies, with high confidence. PROTAC: it is named in the literature on targeted protein degradation; UniProt records ubiquitination sites on it; ubiquitination databases record sites on it; its protein half-life has been measured; a small molecule that binds it is known.
Target class: Structural protein
Gene: Protein-coding gene on chromosome 17 (7,187,187 to 7,219,836, reverse strand). Ensembl gene ENSG00000132535.
Subcellular location: Cell membrane; Postsynaptic density; Synapse; Cytoplasm; Cell projection, axon; Cell projection, dendritic spine; Cell projection, dendrite; Presynapse
Subcellular location (Human Protein Atlas): Basal body; Centrosome; Nucleoplasm; Cytosol; Plasma membrane; Primary cilium; Primary cilium tip
Pathways (Reactome):
Neuronal System: Activation of Ca-permeable Kainate Receptor; Assembly and cell surface presentation of NMDA receptors; Long-term potentiation; Negative regulation of NMDA receptor-mediated neuronal transmission; Neurexins and neuroligins; Ras activation upon Ca2+ influx through NMDA receptor; Synaptic adhesion-like molecules; Trafficking of AMPA receptors; Unblocking of NMDA receptors, glutamate binding and activation
Signal Transduction: RAF/MAP kinase cascade; RHO GTPases activate CIT; Signaling by ERBB4
Developmental Biology: LGI-ADAM interactions; NrCAM interactions
Gene Ontology:
Molecular function: kinase binding; protein binding; acetylcholine receptor binding; beta-1 adrenergic receptor binding; D1 dopamine receptor binding; ionotropic glutamate receptor binding; neuroligin family protein binding; P2Y1 nucleotide receptor binding; PDZ domain binding; protein kinase binding; protein phosphatase binding; protein-containing complex binding; protein-macromolecule adaptor activity; scaffold protein binding; structural constituent of postsynaptic density; synaptic receptor adaptor activity
Biological process: establishment of protein localization; protein localization to synapse; protein-containing complex assembly; AMPA glutamate receptor clustering; cell-cell adhesion; cellular response to potassium ion; chemical synaptic transmission; dendritic spine morphogenesis; establishment or maintenance of epithelial cell apical/basal polarity; learning; long-term synaptic depression; negative regulation of receptor internalization; nervous system development; NMDA selective glutamate receptor signaling pathway; positive regulation of cytosolic calcium ion concentration; positive regulation of excitatory postsynaptic potential; positive regulation of neuron projection arborization; positive regulation of synaptic transmission; receptor localization to synapse; regulation of long-term neuronal synaptic plasticity; regulation of postsynaptic membrane neurotransmitter receptor levels; signal transduction; synaptic vesicle maturation; locomotory exploration behavior; maintenance of postsynaptic density structure; and 5 more
Cellular component: cortical cytoskeleton; plasma membrane; postsynaptic membrane; synapse; adherens junction; AMPA glutamate receptor complex; cell junction; cytoplasm; cytosol; dendrite cytoplasm; dendritic spine; endocytic vesicle membrane; endoplasmic reticulum; excitatory synapse; juxtaparanode region of axon; neuromuscular junction; neuron projection; neuron projection terminus; neuron spine; postsynaptic density; postsynaptic density membrane; postsynaptic density, intracellular component; presynapse; synaptic membrane; synaptic vesicle; and 9 more
Genetic constraint (gnomAD): Loss-of-function variants: 7 observed, 86.95 expected, observed/expected ratio (o/e) 0.0805, 90% interval 0.045 to 0.15. The upper end of that interval is the gene's LOEUF score, 0.15, which puts it in group 1 of 6, group 1 being the genes least tolerant of losing a copy. Missense variants: 545 observed, 954.84 expected, observed/expected ratio (o/e) 0.57, 90% interval 0.53 to 0.61. Synonymous variants: 341 observed, 378.41 expected, observed/expected ratio (o/e) 0.9, 90% interval 0.82 to 0.99.
Gene-disease validity (ClinGen):
ClinGen rates the evidence that DLG4 causes each of these diseases.
complex neurodevelopmental disorder (autosomal dominant): Definitive. A disorder that involves more than one phenotype associated with the central nervous system, including but not limited to intellectual disability, autism, and seizures (epilepsy).
Homologues: Orthologues: rat Dlg4 (99% identical), chimpanzee DLG4 (99% identical), rabbit DLG4 (99% identical), dog DLG4 (99% identical), mouse Dlg4 (99% identical), pig DLG4 (96% identical), guinea pig DLG4 (94% identical), macaque DLG4 (90% identical), zebrafish dlg4a (77% identical), zebrafish DLG4 (50% identical), tropical clawed frog DLG4 (28% identical). Paralogues in human: DLG1 (74% identical), DLG2 (71% identical), DLG3 (64% identical).
Diseases named in the same sentence as DLG4 in open-access papers:
DLG4 is named in the same sentence as 166 diseases in open-access papers, as found by Europe PMC text mining. Sharing a sentence is not in itself a finding about the gene and the disease. The quoted sentences say what the papers report.
Cognitive impairment (130 papers, 2014 to 2026). Abnormal cognition is characterized by deficits in thinking, reasoning, or remembering. "Patients with DLG4 variants typically experience early-onset epilepsy, often alongside cognitive impairment, ASD, and speech delays." (PMID 39596051, 2024). "This synaptic instability makes individuals with DLG4 variants particularly vulnerable to epileptic encephalopathies, where ongoing seizures further compound neurodevelopmental delays and cognitive impairment." (PMID 39596051, 2024). "This identified DLG4 within a small module of 24 genes involved with synaptic function, in which de novo and more severe missense mutations were more likely in individuals with significantly higher intellectual impairment." (PMID 28874660, 2017). "Additionally, in Dlg4−/− mice, cognitive deficits were observed during adulthood, therefore indicate persistent physiological aberrations." (PMID 31263190, 2019). "Thus, epigenetic editing of DLG4 may serve as a novel therapy for rescuing cognitive impairment induced by Alzheimer’s disease." (PMID 33941241, 2021).
depression (89 papers, 2012 to 2026). "Furthermore, impaired stability of dendritic spines, in which PSD95 is a pivotal scaffolding protein, have been implicated in the pathophysiological features of neurological disorders, such as depression, Alzheimer’s disease and DLG4-related synaptopathy." (PMID 37511537, 2023).
schizophrenia (81 papers, 2004 to 2026). A major psychotic disorder characterized by abnormalities in the perception or expression of reality. "In cortical and hippocampal Camk2a neurons, we identified signature proteins linked to epilepsy (e.g., Dlg4) and schizophrenia (e.g., Grin2a)." (PMID 35614064, 2022). "The role of the DLG4 haplotype in schizophrenia susceptibility has been further substantiated in a recent study using Taiwanese cohorts, which showed association of a haplotype spanning the core promoter and 5′-UTR regions with disease." (PMID 23936182, 2013). "FBAT analysis of Japanese schizophrenia pedigrees in the first stage, showed significant association of rs17203281 in DLG4 with a preferential transmission of the C allele (Z = 2.239, p = 0.02)." (PMID 23936182, 2013). "By performing a three staged genetic analysis in independent cohorts of Japanese and Chinese schizophrenia patients, our study aimed to investigate the role of genomic variants in DLG4, DLG1, PICK1 and MDM2 in determining the predisposition to schizophrenia." (PMID 23936182, 2013). "We tested the observed allelic and haplotypic association of DLG4 in 293 schizophrenia pedigree samples of Han Chinese ancestry." (PMID 23936182, 2013). "The current study highlights a putative role for DLG4 in schizophrenia pathogenesis, evidenced by haplotype association, and warrants further dense screening for variants within these haplotypes." (PMID 23936182, 2013). "To conclude, our study identified haplotypes in DLG4 that confer a risk for schizophrenia in Japanese and Chinese populations." (PMID 23936182, 2013). "In summary, we characterized a specific haplotype at the promoter and a SNP at the 3′UTR of the DLG4 gene that were associated with increased liability to schizophrenia." (PMID 21151988, 2010). "We did not detect any rare mutations at the protein-coding sequences of the DLG4 gene associated with schizophrenia." (PMID 21151988, 2010). "Case control association analysis of the DLG4 in Japanese schizophrenia patients." (PMID 23936182, 2013). "Furthermore, the DLG4 gene that encodes the PSD95 was mapped to chromosome 17p13.1, a region linked to schizophrenia." (PMID 21151988, 2010). "The study aimed to investigate whether there are genetic variants of the DLG4 that may confer an increased risk to schizophrenia." (PMID 21151988, 2010). "Taken together, the present study suggests reduced DLG4 gene expression may confer increased risk to schizophrenia." (PMID 21151988, 2010). "The study aimed to examine whether the DLG4 gene that encodes the PSD95 may confer genetic susceptibility to schizophrenia." (PMID 21151988, 2010). "Based on the genetic and functional analysis of the DLG4 gene in the present study, we suggest that subjects carrying the C-D haplotype that is associated with schizophrenia and shows a significant low reporter gene activity may have a reduced expression of PSD95." (PMID 21151988, 2010). "This case describes a pediatric female who was diagnosed with early-onset schizophrenia and catatonia in her early adolescence, and was later found to have DLG4-related synaptopathy, also known as SHINE syndrome." (PMID 37386468, 2023). "NMDA receptors, which are highly influenced by DLG4, are important in many neuropsychiatric disorders that have a cognitive flexibility impairment, e.g., schizophrenia." (PMID 36561312, 2022). "Few studies had linked DLG4 variants to schizophrenia and NDDs such as ID and ASD; DLG2 variants to ASD, schizophrenia, and bipolar disorder; and truncating DLG3 variants to X-linked ID." (PMID 35457207, 2022). "As explained in section 6, DLGAPs influence NMDA receptor synaptic scaling via DLG4 and both DLG4 and DLGAP1 have been linked to schizophrenia." (PMID 28870203, 2017). "In this study, we first performed family-based association analysis of genetic variants in the PSD genes; DLG4, DLG1, PICK1 and MDM2 using Japanese schizophrenia pedigrees." (PMID 23936182, 2013).
schizophrenia (continued). "Although initial analysis showed significant association of the synonymous DLG4 variant, rs17203281, with over-transmission of the C allele, this association result could not be replicated in an ethnically close Chinese pedigree sample set, or in a Japanese schizophrenia case-control cohort." (PMID 23936182, 2013). "Even though expression level changes of DLG4 have been reported in schizophrenia brains, these findings conflict with previous study results." (PMID 23936182, 2013). "Two other schizophrenia susceptibility genes are NRG1 and ERBB4, which are part of the “signaling by ERBB4” and “long-term potentiation” pathway together with DLG4." (PMID 36561312, 2022). "Even if some mechanisms may compensate for the deficiency of PSD-95, a genetic association of the DLG4 gene with autism and schizophrenia was demonstrated." (PMID 33519375, 2020). "Dlg4, also known as PSD-95, plays key roles in synaptic plasticity, spine growth, and AMPA and NMDA receptor regulation, and its dysfunction underlies neuropsychiatric disorders such as schizophrenia and autism." (PMID 31978946, 2020). "The link of DLG1, DLG2 and DLG4 to schizophrenia has been well documented." (PMID 28870203, 2017). "Other studies did not detect any mutations at the protein-coding sequences of DLG4 in schizophrenia populations, but found associations that suggest that the expression of DLG4 is tied to the susceptibility of schizophrenia." (PMID 25506321, 2014). "FBAT analysis of the DLG4 in Japanese schizophrenia pedigree samples." (PMID 23936182, 2013). "DLG4 haplotype comparison in Japanese and Chinese schizophrenia pedigree samples." (PMID 23936182, 2013). "In addition, the DLG4 and PICK1 genes, map to chromosome 17p13.1 and 22q13.1, respectively, regions that are known schizophrenia susceptibility loci, making them ideal positional candidates to screen for schizophrenia genetic predisposition." (PMID 23936182, 2013). "FBAT analysis of the DLG4 in Chinese schizophrenia pedigree samples." (PMID 23936182, 2013). "Thus, the DLG4 gene is a reasonable candidate gene of schizophrenia in view of the high genetic basis of the etiology of schizophrenia." (PMID 21151988, 2010). "Our data indicate that the expression of the DLG4 gene is subject to regulation by the polymorphic markers at the core promoter region, 5′ and 3′UTR of the gene, and is associated with the susceptibility of schizophrenia." (PMID 21151988, 2010). "After sequencing all the protein-coding regions of the DLG4 gene in our patients, we did not identify any mutations associated with schizophrenia in this sample." (PMID 21151988, 2010). "There is no known association between DLG4 and schizophrenia in the literature; notwithstanding this, because there are constant controversial debates on the genetic factors contributing to schizophrenia, DLG4 is greatly deserving of further investigation." (PMID 19379523, 2009). "However, to our knowledge, no mutations of the DLG4 gene associated with schizophrenia have been identified so far." (PMID 21151988, 2010). "pH accounted for significant amounts of variance in parvalbumin (12%), somatostatin (36%), DLG4 (13%) and PPP1R9B (11%) in the schizophrenia group." (PMID 22545112, 2012). "The interactions among DTNBP1, DLG4 and EXOC4 are present in various brain tissues, such as prefrontal cortex and temporal lobe, which are known to be related to schizophrenia etiology." (PMID 19379523, 2009). "The DLG4 expression levels between postmortem brain samples from schizophrenia patients showed no significant changes from controls." (PMID 23936182, 2013). "The roles of DLG4 and EXOC4 in schizophrenia remain to be explored, and the two genes might serve as putative risk markers with potential for further studies." (PMID 19379523, 2009).
schizophrenia (continued). "Since an allelic association was observed for DLG4, gene expression analysis in the dorsolateral prefrontal cortex, BA46 and hippocampal CA1 regions of schizophrenia patient samples was performed, but showed no significant changes between patient and control samples." (PMID 23936182, 2013). "In order to put changes in TNFSF13 mRNA levels in the context of known schizophrenia neuropathology, we explored the relationship between levels of TNFSF13 mRNA and transcript levels of interneuron markers, somatostatin and parvalbumin, as well as spine markers, DLG4 and PPP1R9B." (PMID 22545112, 2012). "Moreover, there was no aberrant change in DLG4 gene expression in schizophrenia brain tissues." (PMID 23936182, 2013). "In this study, we did not observe any significant changes in DLG4 expression levels within the brain regions of BA46 and CA1 in schizophrenia patients, a result which mirrors the observations of a recent study." (PMID 23936182, 2013). "This suggests that DLG4 and PPP1R9B mRNA levels may not closely reflect the morphological changes observed in dendritic spines in patients with schizophrenia." (PMID 22545112, 2012).
Stroke (68 papers, 2012 to 2026). Sudden impairment of blood flow to a part of the brain due to occlusion or rupture of an artery to the brain. "We showed that the expression of Dlg4, Gria1, Grin2a, Gng3, Gnb5, MapK8, and Bdnf (encoding PSD-95, GluA1, GluNMDA2A, G-protein subunit gamma 3, G-protein subunit beta 5, JNK, and BDNF, respectively) was strongly reduced 1 week after stroke." (PMID 31888302, 2019). "Other examples include CASP8 with cancer, NFKB2 with IBD, and DLG4 with stroke." (PMID 33990562, 2021). "These include the model’s limited clinical relevance to human stroke patients, possible variability of results due to differences in surgical techniques and anesthesia, unclear mechanisms by which Dlg4 provides neuroprotection, and a lack of evaluation of potential effects beyond the brain." (PMID 37525090, 2023).
Alzheimer disease (67 papers, 2012 to 2026). A progressive, neurodegenerative disease characterized by loss of function and death of nerve cells in several areas of the brain leading to loss of cognitive function such as memory and language. "For example, the first ranked putative target, DLG4, encodes PSD95, which is a key protein for synaptic plasticity that is downregulated in under aged patients as well as patients with Alzheimer’s disease." (PMID 33941241, 2021). "Meanwhile, increasing the expression of Dlg4/PSD95 through epigenetic mechanisms rescued learning and memory deficits in aged and Alzheimer’s disease mice." (PMID 31005955, 2019). "We applied our computational framework to prioritize novel putative target genes for Alzheimer’s disease and successfully identified key genes that may serve as novel therapeutic targets (e.g., DLG4, EGFR, RAC1, SYK, PTK2B, SOCS1)." (PMID 33941241, 2021).